ADAMTS5 (ADAM metallopeptidase with thrombospondin type 1 motif 5)
Diseases named in the same sentence as ADAMTS5 in open-access papers (continued):
Sharing a sentence is not in itself a finding about the gene and the disease.
tumor (continued). "Moreover, some tumor regions close to large blood vessels were encircled by ADAMTS-5 and Fibulin-2 positive cells." (PMID 28099917, 2017). "In IDC II and IDC II–III, Fibulin-2 was in the periductal and perivascular stroma or in some well delimited cells of the tumor cells masses; whereas ADAMTS-5 showed a faint immunoreactivity paralleled to that of Fibulin-2 or diffusely presented in masses of epithelial cells." (PMID 28099917, 2017). "We also wanted to evaluate whether a potential degradation of Fibulin-2 by ADAMTS-5 could promote other changes in the tumor microenvironment." (PMID 28099917, 2017). "Taking into account these results, it could be hypothesized that ADAMTS-12 protects Fibulin-2 from the degradation mediated by ADAMTS-5, which could influence the equilibrium between tumor-promoting and tumor-preventing functions attributed to Fibulin-2." (PMID 28099917, 2017). "Hence, it is possible that ADAMTS-4 and mainly ADAMTS-5 play a key role in tumor progression to higher stages of CRC by degrading ECM, so as to facilitate cancer cell invasion, in a similar manner as it has been previously demonstrated for hyaluronidase." (PMID 25786261, 2015). "Overexpression of ADAMTS5 in B16 mouse melanoma suppressed primary tumor growth." (PMID 24213506, 2012). "Thus, most likely, ADAMTS5 is bringing about tumor growth suppression through inhibiting angiogenesis." (PMID 24213506, 2012). "So, all these studies suggest a possible tumor suppressor function of ADAMTS5, which may be a consequence of its ability to inhibit tumor angiogenesis." (PMID 24213506, 2012). "Consequently ADAMTS-5 could remain inactivate despite of its high expression in some tumor tissues samples." (PMID 28099917, 2017). "Thus, it can be hypothesized that cleavage of Fibulin-2 by ADAMTS-5 could form part of the strategies employed by tumor cells to degrade ECM components thereby facilitating tumor cell invasion." (PMID 28099917, 2017). "Our study confirmed that miR-145 acts as a tumor suppressor in the occurrence and development of BLCA by down-regulating ADAMTS5." (PMID 40937200, 2025). "The results showed an increased expression of ADAMTS5, CDCA8, and LDHA in tumor tissues, suggesting their significant regulatory roles in HCC." (PMID 40647517, 2025). "In the subcutaneous xenograft mouse tumorigenesis model, B16 melanoma cells overexpressing full-length ADAMTS5 and TS5-p45 truncate both suppressed tumor angiogenesis and enhanced apoptosis within the tumor, resulting in tumor growth suppression." (PMID 35197459, 2022). "Conversely, TQ treatment resulted in the downregulation of several genes overexpressed in GBM cells, including potential oncogenes like AEBP1, MIAT, GHR, LMO1, ELF3, and genes involved in tumor proliferation and migration such as EPHA4, COL3A1, PCDH10, ROBO1, ADAMTS5, PCDH18, ST8SIA1." (PMID 39874307, 2025). "Furthermore, overexpression of ADAMTS5 leads to down-regulation of key angiogenic growth factors such as VEGF, placenta growth factor (PlGF), and platelet-derived endothelial growth factor (PD-ECGF) in the tumor milieu." (PMID 24213506, 2012).
cancer (32 papers, 2005 to 2026). A tumor composed of atypical neoplastic, often pleomorphic cells that invade other tissues. "A recent study has shown that Rab25 upregulates ADAMTS5 in OC through NF-κB signaling and is necessary to stimulate OC cell invasiveness through 3D cancer-associated fibroblast (CAF) matrices, which was reduced by ADAMTS5 inhibition." (PMID 41596584, 2026). "Recent studies found that ADAMTS5 is involved in the tumorigenesis and progression of various cancers." (PMID 40937200, 2025). "Functionally, ADAMTS5 proved sufficient to promote cancer cell migration and invasion across 3D matrices." (PMID 40406984, 2025). "Here, we add ADAMTS5 as a novel anti-cancer/anti-angiogenic ligand of cell surface NCL, inhibiting angiogenesis by triggering EC apoptosis." (PMID 35197459, 2022). "It was found that higher ADAMTS5 expression had a significant association with development and poorer survival of HCC, and its impact on prognosis was specific for HCC among other cancer types from TCGA project." (PMID 35646665, 2022). "RT-PCR and western blotting analyses in cultured cells of three different cancer cell lines revealed that expression levels of ADAMTS-5 were stronger related to cancer aggressiveness, as compared to ADAMTS-4." (PMID 25786261, 2015). "Apart from its active form, ADAMTS-4 was also present in its latent form, while ADAMTS-5 was constantly present in its active form during cancer progression." (PMID 25786261, 2015). "In OC, ADAMTS5 expression was found significantly increased in malignant tumour samples compared to borderline and benign tumours, suggesting that ADAMTS5 could promote OC metastasis." (PMID 40164572, 2025). "Importantly, the inhibition of ADAMTS5's catalytic activity impaired pseudopodia elongation and reduced the directional persistence of migrating cancer cells—but only in the presence of the CAF‐derived matrix." (PMID 40406984, 2025). "Likewise, high ADAMTS5 expression levels in CRC patients are correlated to cancer lymphatic invasion and lymphatic metastasis, suggesting a link between ADAMTS5 and CRC progression." (PMID 38948119, 2024). "Of all the differentially expressed genes, secreted signaling proteins Tgfb2, Il-6, Cxcl1, and Ctgf and metallopeptidases Mmp13, Adamts4, and Adamts5 were of particular interest, as these genes have previously been shown to play a role in regulating cancer migration and invasion and bone remodeling." (PMID 27600237, 2015). "However, contrasting roles for ADAMTS5 have been reported with regards to cancer." (PMID 29891754, 2018). "Hence, it could be suggested that among these two enzymes, ADAMTS-5 was over-expressed mainly in mediate/highly-aggressive cancer cells, while ADAMTS-4 performed a wider range of expression, regardless of cancer aggressiveness." (PMID 25786261, 2015). "Hence, ADAMTS5 might have different roles in different cancers depending on its substrate availability in different tissues." (PMID 24213506, 2012). "Based on its high TargetScores and relevance to cancer, particularly as an unfavorable prognostic marker of RCC, ADAMTS5 was selected for further investigation." (PMID 39575481, 2025). "This component features COL10A1, ITIH5, ADIPOQ, ADAMTS5, GPC3, SFRP1, and RARRES2 genes, pointing to their involvement in cancer-related cellular structures." (PMID 38253993, 2024). "Members of the ADAMTS family, such as ADAMTS2, ADAMTS5, ADAMTS12, and ADAMTS15, can act as cancer suppressors or promoters." (PMID 33921267, 2021). "Following the same experimental procedure, ADAMTS-5 active form was observed in PBS and GdnHCl extracts of healthy colon but also of all cancer stages, however, with a stage-related increased immunoreactivity." (PMID 25786261, 2015). "miR-144 inhibits cancer cell metastasis by targeting the A disintegrin and metalloproteinase (ADAM) protein family member ADAMTS5." (PMID 25927670, 2015).
cancer (continued). "In many cancers, HERV LTRs have been observed to drive cancer-specific or tissue-specific transcripts, including oncogenes such as ADAM metallopeptidase with thrombospondin type 1 motif 5 (ADAMTS5), which is specifically controlled by the LTR mammalian LTR transposon 1J2 (MLT1J2) in thyroid tissues." (PMID 39770638, 2024). "We further demonstrated that the anti-angiogenic/anti-cancer activity of ADAMTS5 is independent of its metalloproteinase activity but is mediated through its central thrombospondin type 1 repeat domain (TSR1)." (PMID 35197459, 2022). "Members such as ADAMTS2, ADAMTS5, ADAMTS12, and ADAMTS15 act as cancer suppressors or promoters." (PMID 33921267, 2021). "ADAMTS5 is overexpressed in CRC, promoting CRC metastasis and cancer cell invasion." (PMID 33258470, 2020).
degenerative disease (4 papers, 2013 to 2025). "In OA, a progressive degenerative disease, proteolytic degradation of cartilage by matrix-degrading enzymes, such as MMP-13 and ADAMTS5, is a hallmark." (PMID 24007463, 2013).
infection (4 papers, 2016 to 2023). The state of being infected such as from the introduction of a foreign agent such as serum, vaccine, antigenic substance or organism. "To investigate the role of ADAMTS5 in influenza virus infection, we initially examined in vivo weight loss and lung virus replication kinetics following infection." (PMID 27855162, 2016). "We set out to assess the contribution of a specific extracellular matrix enzyme, ADAMTS5, to migration of lymphocytes and overall pathogenesis following infection." (PMID 27855162, 2016). "We observed decreased numbers of total CD4+ and CD8+ T cells in the spleen and lung of Adamts5-/- mice at days 7 and 10 following infection." (PMID 27855162, 2016). "This work suggests that ADAMTS5 is necessary for immune cell migration to the periphery, where lymphocyte function is required to fight infection." (PMID 27855162, 2016). "As such, we concluded that Adamts5-/- mice were immunologically “normal” prior to infection." (PMID 27855162, 2016). "We intranasally infected Adamts5-/- mice and C57.BL/6 controls with 104 pfu/mouse-adapted X31 (H3N2) influenza virus, and observed enhanced weight loss (p < 0.05 on day 8 p.i.)in Adamts5-/- mice across the experimental infection period when compared to C57.BL/6 controls." (PMID 27855162, 2016). "To do this, we overexpressed Prok2 in primary-culture chondrocytes using Ad-Prok2 infection and evaluated the expression levels of key matrix-degrading enzymes, including MMP3, MMP13, and ADAMTS5, which play pivotal roles in cartilage degradation during OA pathogenesis." (PMID 38057865, 2023). "Thus, we propose that cleavage and removal of versican blockades via the action of proteoglycanases, such as ADAMTS5, is required for efficient T cell interaction with the ECM to encourage migration to effector sites in the periphery and for the subsequent resolution of infection." (PMID 27855162, 2016). "In chondrocytes overexpressing ERRγ via infection with Ad-Esrrg, MMP-3 and MMP-13 mRNA levels were dramatically elevated without affecting MMP-12 and ADAMTS5." (PMID 33261216, 2020).
metabolic disorder (3 papers, 2023 to 2024). "In this study, Glycitin effectively reversed the TNF-α-mediated loss of Col-2 and Aggrecan, and reduced the level of MMP-13 and ADAMTS-5, suggesting that Glycitin is a key role in metabolic disorders of IVD." (PMID 38019477, 2023). "Our results show that FG@F can offset the negative impact of substrate metabolic disorder caused by matrix loss and ADAMTS-5 expression." (PMID 37968507, 2023). "Then qPCR and Western blotting revealed that Se-Met supplementation reduced the production of ADAMTS-5 and MMP-13 and promoted the secretion of Aggrecan and Col-2 in response to mechanical overloading, while additional ML210 aggravated ECM metabolic disorder." (PMID 38252317, 2024). "Besides, the qPCR and Western blotting revealed that Se-Met supplementation reduced the production of ADAMTS-5 and MMP-13, and promoted the secretion of Aggrecan and Col-2, while knockdown of SelK aggravated ECM metabolic disorders." (PMID 38252317, 2024).
benign tumours (2 papers, 2014 to 2025). "PPS also suppresses the activity of ADAMTS5, inflammatory mediators, and coagulation factors, effects that may contribute to the observed beneficial effect in the pressure-overloaded heart." (PMID 24595230, 2014).
bacterial infections (1 paper, 2024). "ADAMTS-5 and MMP-3 were identified as key enzymes involved in matrix catabolism during different phases of disc degeneration induced by the respective bacterial infections." (PMID 38297365, 2024).
cardiovascular diseases (1 paper, 2024). "Selectivity over ADAMTS5 is important because this enzyme represents an anti-target in cardiovascular diseases." (PMID 39149096, 2024).
kidney (1 paper, 2020). "ADAMTS5 is likely expressed in IgAN as well as other kidney pathologies, by infiltrating monocytes and might play a role in matrix turnover and scarring." (PMID 32917786, 2020).
kidney diseases (1 paper, 2020). "ADAMTS5 might be a therapeutic target in kidney disease given that inflammatory kidney scarring is associated with loss of renal function." (PMID 32917786, 2020). "The expression and function of ADAMTS5 in IgAN or kidney disease is unknown." (PMID 32917786, 2020). "The expression of ADAMTS5 in other kidney diseases is not surprising given that the enzyme is apparently enriched in classical monocytes." (PMID 32917786, 2020). "Pharmacologically, it might be more feasible to target a proteolytic enzyme rather than the entire inflammatory process, so targeting ADAMTS5 as a possible antiremodelling therapy could be relevant in IgAN and other kidney diseases with an inflammatory and scarring component." (PMID 32917786, 2020).
ADAMTS5 also shares sentences with these, for which no sentence is quoted: non-small cell lung carcinoma (3 papers); osteoporosis (3); aortic aneurysm (2); Bladder Urothelial Carcinoma (2); connective tissue disorder (2); endometriosis (2); invasive ductal breast carcinoma (2); juvenile idiopathic arthritis (2); osteosclerosis (2); age (1); aneurysmal disease (1); Anxiety (1); Cachexia (1); calcific aortic valve disease (1); cardiac ischemia (1); depression (1); developmental delay (1); digestive system tumors (1); endometrial cancer (1); genetic disorders (1); glaucoma (1); head and neck squamous cell carcinoma (1); hemophilia (1); Hypertension (1); hypertrophic cardiomyopathy (1); IgA Nephropathy (1); Infertility (1); Intellectual disability (1); Lewis lung carcinoma (1); lymphedema (1).
A further 17 diseases each share a sentence with ADAMTS5 in 1 paper.